TNF (tumor necrosis factor)
Diseases named in the same sentence as TNF in open-access papers (continued):
Sharing a sentence is not in itself a finding about the gene and the disease.
ischemic stroke (continued). "A total of 81 DEGs were in the molecular network of STAT1 targets, including genes encoding the proinflammatory cytokines IL-1β, tumor necrosis factor alpha (TNF-α), and IL-12, all of which were upregulated in microglia after ischemic stroke." (PMID 37516843, 2023). "We conclude that there is a possible strong association between the VWF-T > C, TNF-alpha G > A, GSTT1 gene variants and ischemic stroke susceptibility in the Saudi population." (PMID 37240845, 2023). "In this study, we evaluated the association of the VWF rs61748511 T > C, TNF-alpha rs1800629 G > A and GST rs4025935, rs71748309 gene variants with risk of ischemic stroke in the Saudi population." (PMID 37240845, 2023). "IL-6, AKT1, VEGFA, STAT3, TNFα, etc., were the core target of phenolic acids in preventing ischemic stroke." (PMID 36778026, 2023). "TNF-α exerts different effects in the context of ischemic stroke showing both neuroprotective and detrimental characteristics." (PMID 36745280, 2023). "All this reveals the clinical value of HBOT as a treatment for ischemic stroke which can modulate inflammatory responses, reduce IL-6 and TNF-α expression, and protect against ADRs." (PMID 37250560, 2023). "Previous studies using Tnf-knockout mice showed that TNF-α was neuroprotective in ischemic stroke, while pharmacologically blocking TNF-α attenuated brain injury." (PMID 37486903, 2023). "Studies have shown that EP can reduce proinflammatory cytokines, such as TNF‐α and IL‐6, thereby inhibiting inflammation in ischemic stroke." (PMID 37143406, 2023). "Once recruited to the ischemic hemisphere, classical monocytes secrete proinflammatory cytokines, including IL‐1/6 and TNF‐α, which promote inflammation, affect the infarcted tissue, and aggravate ischemic injury in ischemic stroke." (PMID 37452512, 2023). "Common polymorphisms in the TNF-α gene promoter result in elevated TNF-α levels, which appear to be associated with cardiovascular risk factors and ischemic stroke in Asians." (PMID 36769472, 2023). "In the early phase of experimental ischemic stroke, microglia produce pro-inflammatory mediators such as TNF-α, IL-1β and reactive oxygen species resulting in further damage and secondary cell death in the penumbra region." (PMID 37193998, 2023). "In previous studies, proinflammatory cytokines such as IL-6 and TNF-α that glial cells secrete, induce inflammation in ischemic stroke." (PMID 37107160, 2023). "The NIHSS score, infarct volume and the levels of NLRP1, IL-6, TNF-α, and IL-1β of ischemic stroke patients in the mRS score ≥ 3 group were remarkably elevated than the ischemic stroke patients in the mRS score ≤ 2 group." (PMID 37000063, 2023). "CCR6 activation is associated majorly with early IL-17 production in acute infections and after ischemic stroke, IL-17 triggers the expression of TNF-α and chemokines." (PMID 35453602, 2022). "This response is an important pathological mechanism through which large amounts of TNF-α are released in ischemic stroke, thus worsening PSN." (PMID 36389810, 2022). "Previous reports showed that JQ1-treated animals exhibit a marked reduction in the expression of pro-inflammatory mediators IL-1β, IL-6, IL-17, IL-18, and TNF-α in the brain in rodent ischemic stroke models." (PMID 35761277, 2022). "Accumulated studies have explored gene polymorphisms and circulating levels of tumor necrosis factor (TNF)-α and insulin-like growth factor (IGF)-1 in the etiology of ischemic stroke (IS)." (PMID 35370618, 2022). "We previously reported that H19 increases the immune response by increasing plasma TNF‐α and IL‐1β levels after ischemic stroke; moreover, it affects the subsequent pathological outcome." (PMID 35322553, 2022). "TNF-signaling plays pleiotropic and multiple roles in ischemic stroke, including acute inflammation and cell death during the early stages and tissue repair during the later recovery phase." (PMID 35250546, 2022).
ischemic stroke (continued). "Microglia release proinflammatory cytokines such as IL-1β, IL-6, and TNF-α in the acute phase of ischemic stroke, impeding postinjury neural regeneration and producing poorer long-term neurological outcomes." (PMID 36338577, 2022). "It is found in research on nerve diseases that DNTs can promote microglial cell activation in mice with ischemic stroke to exert the pro-inflammatory effect, and such effect was related to TNF-α secretion." (PMID 35371052, 2022). "In the occurrence of ischemic stroke, monocyte macrophages and T lymphocytes are stimulated to produce inflammatory cytokines, such as tumor necrosis factor α (TNF-α), interleukin 6 (IL-6), and interleukin 1 (IL-1), which have immunomodulatory function." (PMID 35340417, 2022). "Numerous studies have shown that TNF-α plays a double-sided role in the pathophysiology of ischemic stroke." (PMID 36211352, 2022). "TNF-α can be secreted by a variety of immune cells, but it is mainly secreted by microglia and monocytes after ischemic stroke." (PMID 36211352, 2022). "The expression of pro-inflammatory cytokines (IL-1β, IL-6, IL-8, TNF-α) in the cortex of ischemic stroke mice was detected after the occurrence of cerebral ischemia." (PMID 35173738, 2022). "Intraventricular MCS transplantation, performed 1 day post ischemic stroke, reportedly upregulated IL-10 and reduced tumor necrosis factor (TNF)-alpha 4 days post ischemic stroke." (PMID 36671605, 2022). "The results of our study indicate that TNF-α released by astrocytes promote platelet aggregation in the cerebral cortex during ischemic stroke by activating the TNFR/RIP1/RIP3/AKT pathway." (PMID 35781632, 2022). "Given the role played by platelets in the pathogenesis of ischemic stroke, we analyzed the functional relationship between TNF-α secretion and platelet aggregation in vivo." (PMID 35781632, 2022). "Consistent with the network pharmacology findings, in the current study, it is revealed that IL-1β, TNF-α, IL-6, and IL-4 were significantly increased in the cerebral cortex and hippocampus after ischemic stroke." (PMID 36338345, 2022). "Taken together, TNF-α secreted by astrocytes plays an important role in the pathologic progression of ischemic stroke, and TNF-α blockade can attenuate brain edema and infarct volume following transient MCAO." (PMID 35781632, 2022). "The SVM classifier showed excellent AUC values for discrimination of ischemic stroke and pathway analysis of the immunosuppression-related crosstalk genes showed TNF-signaling among the topmost enriched pathways." (PMID 35250546, 2022). "Microglia and astrocytes are also known producers of IL-1α, which was also found to be elevated in the brains of offspring in this model and, similar to TNFα, has been suggested to be neuroprotective in models of ischemic stroke." (PMID 36009104, 2022). "Although macrophages are the major TNF-α source after ischemic stroke, CD3+CD4-CD8- T cells also secrete TNF-α on day 1 to day 3 and is located around the Iba1+ microglia." (PMID 34335623, 2021). "We here showed that miR-141-3p inhibition shows its neuroprotective effects by reducing pro-inflammatory cytokine TNF-α in young adult mice after ischemic stroke." (PMID 33922958, 2021). "We showed that salivary TNF-α and IL-6 were significantly higher, whereas IL-10 content was statistically lower in ischemic stroke patients than healthy controls." (PMID 34433866, 2021). "In accordance with these observations, increased expression of pro-inflammatory markers (e.g., tumor necrosis factor alpha (TNFα) and Interleukin-1β (IL-1β)) has been described in both animals and humans after an ischemic stroke." (PMID 34685745, 2021). "Immediately after ischemic stroke, A1 astrocytes produce and secrete several proinflammatory mediators, such as IL-6, TNF-α, IL-1α, IL-1β, and IFN-γ." (PMID 34211624, 2021).
ischemic stroke (continued). "Along with TNF-α and IL-1β, IL-6 is also upregulated during the acute inflammatory phase after ischemic stroke and accumulating evidence suggests that elevated IL-6 during acute ischemic stroke is associated with poor functional outcomes." (PMID 34572077, 2021). "Both IL-17 and TNF are thought to play an important role in the inflammatory cascade response in ischemic stroke, so both the IL-17signaling pathway and TNF signaling pathway are intimately involved in the pathological evolution of IS." (PMID 34603472, 2021). "Astrocytes attracted neutrophils in ischemic stroke by increasing the secretion of CXCL1 in response to the synergistic effects of TNF-α and IL-17A." (PMID 34248961, 2021). "During the acute phase of ischemic stroke, TNF-α is produced by leukocytes circulating in the peripheral blood and its expression is highest between 8 and 24 h after the onset of cerebral ischemia." (PMID 34433866, 2021). "Typically, activated microglia are considered a deleterious reaction in ischemic stroke owing to the acute expression of tumor necrosis factor-alpha (TNF-α) that aggravates the neurological deficit." (PMID 34149359, 2021). "A recent study showed that miR-381-3p downregulated Map3k8 to inhibit inflammation and the activation of TNF-α signaling pathway following ischemic stroke." (PMID 33986769, 2021). "Previous work from our group has demonstrated that Poldip2 depletion attenuates TNF and IL-6 levels following ischemic stroke, possibly via regulation of NFκB33." (PMID 33692398, 2021). "An upregulation of TNF-alpha, IL-1beta, and IL-4 gene expression was found in total monocytes 24 and 48 h after an ischemic stroke compared to healthy conditions." (PMID 34201498, 2021). "In ischemic stroke, manifestation of downregulated NF-κB was supplemented by the knockdown of TNF-α, IL-6 and IL-1β." (PMID 33658008, 2021). "TNF-α acts in synergism with IL-1β to enhance neuroinflammation and brain damage after ischemic stroke." (PMID 34572077, 2021). "Previous studies confirmed that CD8+T cells potentiated the progression of ischemic stroke by granzyme-b and FasL induced cytotoxicity and by TNF-α and IFN-γ." (PMID 34248961, 2021). "In experimental models of ischemic stroke, HPA system activity is associated with neuroinflammation, mediated by increased expression of pro-inflammatory cytokines TNFα, IL1β, and IL6." (PMID 34948340, 2021). "HIF-1α knockdown in microglia abrogated hypoxia-induced phagocytosis, production of intracellular reactive oxygen species (ROS) and tumor-necrosis factor α (TNF-α), which protected neuronal survival in the acute phase of ischemic stroke in mice model." (PMID 34881289, 2021). "Inhibition of P-JNK activity rescued microgliosis and suppressed neuroinflammation by reducing the expression levels of TNF-α and IL-1β in ischemic stroke." (PMID 34206065, 2021). "Activated microglia produce a plethora of neurotoxic mediators such as NO, TNF-α, and IL-1β which have direct effects on neurologic outcomes of ischemic stroke." (PMID 33757565, 2021). "Clinical trial results show that musk can reduce the level of TNF-α in patients with ischemic stroke and improve the effectiveness of treatment." (PMID 32714405, 2020). "Gm4419 promoted neuroinflammation by inducing IκB phosphorylation and NF-κB signaling activation after ischemic stroke, and the levels of tumor necrosis factor-α (TNF-α), interleukin-1β (IL-1β) and IL-6 were increased." (PMID 33613191, 2020). "It has been shown that after an ischemic stroke, the blood-brain barrier integrity was influenced by microglia via an up-regulation of pro-inflammatory cytokines including IL-1b, TNF-a, and IL-6." (PMID 32501292, 2020). "Changes in Dectin-1, Syk, p-Syk, TNF-α, and inducible nitric oxide synthase (iNOS) expression following ischemic stroke were evaluated both in vivo and in vitro." (PMID 31926564, 2020).
ischemic stroke (continued). "A major barrier to the efficacy of etanercept as a TNF inhibitor in ischemic stroke, however, is its poor blood-brain barrier (BBB) permeability due to its large size." (PMID 32503645, 2020). "Tumour necrosis factor (TNF) is an immune signalling molecule, centrally involved in ischaemic stroke pathology through its modulation of microglial activation, role in synaptic dysfunction and induction of depressive symptoms and neuropathic pain." (PMID 32168831, 2020). "Accordingly, inhibition or genetic knockdown of the channel has been reported to reduce IL-2 production by T cells and IL-β1 and TNFα levels by microglia in ischemic stroke." (PMID 32150577, 2020). "The activated microglia subsequently release chemokines, cytotoxic mediators, and cytokines, including IL-1β, TNF-α and IL-6, triggering the inflammatory cascade after an ischemic stroke, thus further exacerbating neuroinflammatory damage." (PMID 32419986, 2020). "A previous study also indicated that H19 promoted neuroinflammation by M1 microglial polarization, which lead to increased production of TNF-α and IL-1β in ischemic stroke." (PMID 33613191, 2020). "The Dectin-1 antagonist LAM or Syk inhibitor PIC decreased the number of Iba1-positive cells and TNF-α and iNOS expression, decreased the brain infarct volume, and improved neurological functions on day 3 after ischemic stroke." (PMID 31926564, 2020). "A link has been established between polymorphism of the promoter of the TNF-α gene and increased TNF-α levels, ischaemic stroke and increased TGF-β1 levels with progressive deep white matter lesions in patients with cSVD." (PMID 32485815, 2020). "AMD3100 administration also results in the significant reduction of IFN-γ, TNF-α and IL-6 in the acute stage of ischemic stroke or after spinal cord injury." (PMID 33013914, 2020). "The results support findings from animal studies that IL-1α, IL-1β, IL-1Ra, and TNF are produced by subsets of primarily microglia and leukocytes in ischemic stroke tissue." (PMID 32503645, 2020). "In conclusion, the present study determines the cellular sources of IL-1α, IL-1β, and IL-1Ra in human post-mortem ischemic stroke tissue, and the cellular sources of TNF, TNFR1, and TNFR2 in parallel tissue sections." (PMID 32503645, 2020). "In one study, serum TNF levels did not increase until 4–10 days after symptom onset compared to controls, suggesting that TNF levels only increase in the chronic phase after ischemic stroke." (PMID 32503645, 2020). "Other researches prove that proinflammatory cytokines such as IL-1b, IL-6, and TNF-a are released by microglia and upregulate after ischemic stroke." (PMID 32382569, 2020). "In ischemic stroke, they participate in the regulation of proinflammatory cytokines such as IL-1β and TNF-α by activating the MAPK cascade." (PMID 32714405, 2020). "Various blood-based biomarkers were found to be significantly associated with ischemic stroke from cardioembolic etiology including BNP/NT-proBNP, d-dimer, CRP, TNF-α, IL-6, and IL-1β." (PMID 33050269, 2020). "In summary, our study shows for the first time a previously unexplored role of M1-like microglia-derived TNF-α mediated EC necroptosis in BBB disruption after ischemic stroke." (PMID 31221990, 2019). "Hs-CRP is a systemic inflammatory marker that is produced in large amount by hepatocytes in response to interleukin-1 (IL-1), interleukin-6 (IL-6) and tumor necrotic factor-α (TNF-α) after ischemic stroke." (PMID 31814936, 2019). "As innate immunocytes, microglia were excessively activated and released robust inflammatory cytokines, such as IL-1, IL-6, TNF, and iNOS, immediately after ischemic stroke, which contributed to neuronal apoptosis and thus aggravated brain injury." (PMID 30001721, 2018). "Further, the MHP1 peptide showed an anti-osteoclast activity in ischemic stroke, by suppressing LPS and TNF-α production." (PMID 30208640, 2018).
ischemic stroke (continued). "The combination of EA 2 Hz and melatonin induced an inhibitory effect on COX-2 and TNF-α, playing a key role in neuroprotective effect to alleviate cerebral infarct volume and neurological deficit following ischemic stroke." (PMID 30618558, 2018). "Ischemic stroke significantly increased protein levels of TNF-α in BALF and plasma, as well as of IL-6 in plasma." (PMID 30290827, 2018). "In line with the previous studies, ischemic stroke induced massive production of TNF-α, IL-1β, and IL-6." (PMID 29544517, 2018). "Both in vivo and in vitro ischemic stroke models induced the production of inflammatory mediators, including TNF-α, IL-1β, iNOS, and IL-10." (PMID 28592261, 2017). "We demonstrated that CN‐105 downregulates microglial activation in ischemic stroke and suppress TNF‐α secretion from C8‐B4 microglial cells." (PMID 28382306, 2017). "Inflammatory cytokines such as TNF-α, IL-1β, and IL-6 play pivotal roles in the pathogenesis of ischemic stroke." (PMID 29234386, 2017). "TNF-α levels in cerebrospinal fluid (CSF) and serum of patients with ischemic stroke were markedly increased within 24 h, and this increase in levels of CSF and serum TNF-α was positively correlated with infarct volume." (PMID 28115020, 2017). "Secondly, FGF10 treatment in vivo decreased neuronal apoptosis and inhibited NF-κB signaling activation during ischemic stroke and thereby neuroinflammation (TNF-α and IL-6 production)." (PMID 26813160, 2016). "We demonstrated that estradiol possessed anti‐inflammatory effects including suppressing the serum concentration of IL‐1β and TNF‐α after ischemic stroke in vivo and also in primary microglia culture." (PMID 27127723, 2016). "Etanercept, a TNF‐α antagonist, which has been used therapeutically in animal models of ischemic stroke and neural damage." (PMID 27781140, 2016). "Interleukin‐1β and TNF‐α are produced by a largely segregated population of microglia and infiltrating macrophages after ischemic stroke in mice." (PMID 27781140, 2016). "Attenuation of CX3CL1 signaling by CX3CL1 or CX3CR1 gene knockdown both significantly reduced infarct size, expression of IL-1β and TNF-α, and leukocyte infiltration in ischemic stroke models." (PMID 26860080, 2016). "Cytokines, including interleukin (IL)-1β, IL-6, tumor necrosis factor (TNF)-α, IL-10 and transforming growth factor-β (TGF-β) are associated with inflammation in ischemic stroke." (PMID 25815894, 2015). "Previously higher circulating levels of PAI-1 and TNF-alpha were found in ischemic stroke patients with poor functional outcome." (PMID 26162891, 2015). "TNF-α is a proinflammatory cytokine that is synthesized in the brain within 1 h of an acute experimental ischemic stroke." (PMID 26665003, 2015). "Interleukin-6 (IL-6) interleukin-1 beta (IL-1b), and tumor necrosis factor-alpha (TNF-α) are one of the important atherogenic markers in ischemic stroke patients." (PMID 26075263, 2015). "Melanocortins, which function as cholinergic anti-inflammatory pathway regulators, downregulate tumor necrosis factor-α levels after ischemic stroke in a vagus nerve-dependent manner." (PMID 25009531, 2014). "Of these IL-1α, CYP11B2, ESR1 (PVUII), α ADD1, TNF α (G488A), CYP4F2, MDR-1 and t-PA (I/D) were found to be significantly associated with ischemic stroke." (PMID 23505425, 2013). "Microglial/macrophage production of TNF-α can be measured 6, 12, and 24 hours after ischemic stroke." (PMID 24223607, 2013). "While data for its use in acute CNS injury are limited, especially in ICH, TNF-α antagonism as a therapeutic strategy has gained attention in models of other forms of injury such as ischemic stroke, traumatic brain injury, and spinal cord injury." (PMID 23962089, 2013). "Increasing lines of evidence have demonstrated that TNF-α plays an important role in the development of ischemic stroke." (PMID 24285977, 2013).